NEFL (neurofilament light chain)
Diseases named in the same sentence as NEFL in open-access papers (continued):
Sharing a sentence is not in itself a finding about the gene and the disease.
multiple sclerosis (284 papers, 2005 to 2026). A progressive autoimmune disorder affecting the central nervous system resulting in demyelination. "Serum biomarkers as neurofilament light chain (sNfL) and glial fibrillary acidic protein (sGFAP) enabled early identification of multiple sclerosis (MS) patients at risk of relapse-associated worsening (RAW) or progression independent of relapses (PIRA)." (PMID 40852725, 2025). "The assessment of serum neurofilament light chain (sNFL) has emerged as a diagnostic and prognostic tool in monitoring multiple sclerosis (MS)." (PMID 38426169, 2024). "We discovered 72 proteins associated with multiple sclerosis at a Bonferroni‐adjusted p value of 0.05, including established markers such as neurofilament light chain and glial fibrillary acidic protein." (PMID 38282238, 2024). "In clinically suspected multiple sclerosis, intrathecal immunoglobin G production and neurofilament light chain levels had diagnostic value." (PMID 29614113, 2018). "Neurofilament light chain (NfL) is an axonal cytoskeletal protein that is released into the extracellular space following neuronal or axonal injury associated with neurological conditions such as multiple sclerosis (MS), amyotrophic lateral sclerosis (ALS), and other diseases." (PMID 35959400, 2022). "Serum neurofilament light chain (sNfL), a biomarker of neuroaxonal injury in multiple sclerosis (MS), exemplifies this challenge." (PMID 42279567, 2026). "Serum neurofilament light chain (sNfL) is an established biomarker of disease activity and progression in persons with multiple sclerosis (PwMS), with studies showing elevated sNfL levels during relapses and positive associations with disability scores." (PMID 41419610, 2025). "The neurofilament light chain (NfL) subunit has emerged as a biomarker for axonal injury in various neurological diseases, such as multiple sclerosis (MS), amyotrophic lateral sclerosis (ALS), and traumatic brain injury (TBI)." (PMID 40643487, 2025). "This study focused on neurodegenerative biomarkers in multiple sclerosis—namely, plasma neurofilament light chain (pNfL) levels and magnetic resonance imaging (MRI)-based brain volume measurements." (PMID 40863992, 2025). "Serum neurofilament light chain (sNfL) reflects neuro‐axonal injury, and is an emerging biomarker in multiple sclerosis (MS)." (PMID 41290980, 2025). "Background and aims: Serum neurofilament light chain (sNfL) is a biomarker reflecting neuroaxonal damage in multiple sclerosis (MS)." (PMID 40542581, 2025). "Neurofilament light chain (NfL) has proven its value in multiple sclerosis (MS) as a biomarker not only of disease activity through its correlation with relapse rate and presence of gadolinium-enhancing lesions, but also for prognosis and treatment response." (PMID 41465206, 2025). "Background and aims: To evaluate serum neurofilament light chain (sNFL) levels as a biomarker for treatment efficacy in multiple sclerosis (MS) patients undergoing various disease‐modifying therapies (DMTs), focusing on extended interval dosing (EID) regimens." (PMID 40542581, 2025). "Recent research indicates that multiple sclerosis is preceded by a prodromal phase with elevated levels of serum neurofilament light chain (sNfL), a marker of axonal injury." (PMID 37930324, 2024). "To date, the laboratory tests commercially available for the diagnosis of multiple sclerosis include the measurement of Free Kappa Light Chains (kFLC) and the quantification of Neurofilament Light Chains (NfL) and Glial Fibrillary Acid Protein (GFAP) levels." (PMID 38338973, 2024). "Studies on the capability of cerebrospinal fluid neurofilament light chain (cNfL) to predict multiple sclerosis (MS) conversion in clinically isolated syndromes have yielded varying results." (PMID 39052040, 2024). "Neurofilament light chain (NfL) is also a valuable biomarker for the diagnosis of CNS disorders, including multiple sclerosis." (PMID 38338966, 2024).
multiple sclerosis (continued). "Serum neurofilament light chain (sNfL) is a biomarker of neuroaxonal destruction that correlates with acute inflammation (AI) in multiple sclerosis (MS)." (PMID 39539651, 2024). "Serum neurofilament light chain (sNfL) is an intensely investigated biomarker in multiple sclerosis (MS)." (PMID 36835478, 2023). "In recent years, plasma neurofilament light chain (NfL) protein has emerged as a promising biomarker for neurodegeneration in several neurological diseases (e.g., AD and multiple sclerosis)." (PMID 37491244, 2023). "The plasma or serum level of the neurofilament light chain (NfL) is a biomarker of neuroaxonal damage in multiple sclerosis." (PMID 37241097, 2023). "The neurofilament light chain (NfL) protein, another biomarker for axonal loss, also correlates with CSF CHIT1 levels in patients with ALS and multiple sclerosis." (PMID 36052089, 2022). "Serum neurofilament light chain is a putative biomarker of neurodegeneration in multiple sclerosis, aging, and other neurodegenerative diseases." (PMID 35770318, 2022). "The predictive value of serum neurofilament light chain (sNfL) on long-term prognosis in multiple sclerosis (MS) is still unclear." (PMID 35649699, 2022). "Neurofilament light chain (NfL) in cerebrospinal fluid (CSF) is a biomarker of multiple sclerosis (MS)." (PMID 36103562, 2022). "Measurement of serum neurofilament light chain concentration (sNfL) promises to become a convenient, cost effective and meaningful adjunct for multiple sclerosis (MS) prognostication as well as monitoring disease activity in response to treatment." (PMID 33841093, 2021). "Serum neurofilament light chain (NfL) has been shown to correlate with neuroaxonal damage in multiple sclerosis (MS) and various other neurological diseases." (PMID 32872144, 2020). "Central nervous tissue degeneration promotes disease progression in multiple sclerosis (MS), and neurofilament light chain (NfL) is a validated surrogate biomarker for this process in patients with relapsing-remitting MS (RRMS)." (PMID 32425877, 2020). "The aim of our study was to assess serum glial fibrillary acid protein (s-GFAP) and neurofilament light chain (s-NfL) in a cohort of 129 multiple sclerosis (MS) patients." (PMID 32616916, 2020). "ICC, intraclass correlation coefficient; iCOV, intraindividual coefficient of variance; PD, Parkinson’s disease; iSD, intraindividual standard deviation; MS, multiple sclerosis; sNfL, serum neurofilament light chain concentration [pg/ml]." (PMID 33203974, 2020). "Serum neurofilament light chain (NfL) is emerging as an important biomarker in multiple sclerosis (MS)." (PMID 32587320, 2020). "Neurofilament light chain (NfL) is emerging as a biomarker assessing neuroaxonal damage in patients with multiple sclerosis while knowledge about its relevance in patients with progressive MS is still limited." (PMID 30915022, 2019). "CA19-9 and neurofilament light chain (NFL) reflected peripheral disease biomarkers in pancreatic cancer (PC) and multiple sclerosis (MS), respectively." (PMID 31877665, 2019). "While neurofilament light chain (NfL) measurement in serum is a well-established marker of neuroaxonal damage in multiple sclerosis (MS), data on astroglial markers in serum are missing." (PMID 30287870, 2018). "Various dependable biomarkers, such as MRI assessments, immunoglobulin G (IgG), oligoclonal bands (OCB), and neurofilament light chain (NfL) levels in cerebrospinal fluid (CSF), have been recognized for tracking treatment responses in Multiple Sclerosis (MS) patients." (PMID 40621757, 2025). "Similarly, neurofilament light chain (NfL) is a neuronal cytoskeleton protein, which is a sensitive indicator for neuronal damage in neurological disorders ranging from multiple sclerosis to AD." (PMID 39969743, 2025).
multiple sclerosis (continued). "Neurofilament light chain (NfL), an abundant cytoskeletal protein in neurons, has emerged as a promising serum biomarker that indicates non-specific neuronal damage secondary to various neurologic diseases, including multiple sclerosis (MS)." (PMID 40278427, 2025). "Serum neurofilament light chain (sNfL) levels have been proposed as a biomarker of the clinical activity, disability progression, and response to treatment of people with multiple sclerosis (PwMS); however, questions remain about its implementation in clinical practice." (PMID 39063946, 2024). "For example, increased neurofilament light chain (NfL) levels could indicate Alzheimer's, Multiple Sclerosis and ALS." (PMID 38817373, 2024). "It has been speculated that neurofilament light chain could act as marker of axonal injury in different neurological disorders, including multiple sclerosis, neurodegenerative dementia, stroke, traumatic brain injury, amyotrophic lateral sclerosis and Parkinson disease." (PMID 35297008, 2022). "Although cladribine induces sustained reductions in peripheral T and B lymphocytes, little is known about its effect on axonal damage reduction in multiple sclerosis (MS), which could be demonstrated by assessing the serum neurofilament light chain (sNfL) levels." (PMID 36552055, 2022). "Consequently, NFs and particularly the neurofilament light chain (NfL) subunit recently emerged as promising in-vivo markers of active brain pathology in several neuropsychiatric disorders, including multiple sclerosis, neurodegenerative diseases, traumatic brain injuries, and depression." (PMID 35420371, 2022). "Similarly, neurofilament light chain (NfL) is detected using advanced techniques such as the single molecule array (Simoa) method, providing reliable quantification across AD, Parkinson’s disease (PD), multiple sclerosis (MS), and amyotrophic lateral sclerosis (ALS)." (PMID 40076852, 2025). "Background/Objective: Neurofilament light chain (Nf-L), neurofilament heavy chain (Nf-H), and chitinase 3-like 1 (CHI3L1) are cerebrospinal fluid (CSF) biomarkers of neuroaxonal damage and inflammation in multiple sclerosis (MS)." (PMID 40564113, 2025). "Although neurofilament light chain (Nf-L) is not specific to multiple sclerosis (MS) and is elevated in other neurological conditions, it remains the most investigating and promising biomarker for detecting axonal damage in MS and plays a definitive role in predicting disease progression." (PMID 40564113, 2025).
cognitive decline (276 papers, 2014 to 2026). "One study quantified AD biomarkers in human AH, suggesting that elevated neurofilament light chain (NfL) and phosphorylated tau (p‐tau181) were associated with cognitive decline (lower MMSE scores)." (PMID 40927874, 2025). "An increase in CSF or plasma biomarkers, including Aβ, p-tau, and neurofilament light chain protein (NfL), precedes brain volume loss that can be assessed by brain volumetric MRI and ultimately results in cognitive decline." (PMID 38473975, 2024). "For instance, in one work, combining neuroimaging and blood biomarkers (neurofilament light chain) helped improve the diagnostic accuracy of cognitive decline in MS." (PMID 38454906, 2024). "Plasma neurofilament light chain (NfL), a cytoplasmic protein, is a marker of neurodegeneration associated with cognitive decline, brain atrophy, and hypometabolism." (PMID 38654932, 2024). "Little is known about the association of serum neurofilament light chain (NfL) concentrations and physical activity with the rate of cognitive decline in older adults." (PMID 35315915, 2022). "Is physical activity associated with lower rates of cognitive decline in older adults with higher serum concentrations of neurofilament light chain (NfL)?" (PMID 35315915, 2022). "Notably, neurofilament light chain had a stronger association with retinal thinning than phosphorylated tau181 and offered superior diagnostic value for identifying moderate cognitive decline." (PMID 39749011, 2025). "Delirium is linked with poor outcomes, such as prolonged hospital stays, increased mortality, and cognitive decline related to neuronal damage, as indicated by elevated serum neurofilament light chain (NfL) levels." (PMID 41219650, 2025). "Elevated neurofilament light chain (NfL) levels in cerebrospinal fluid and plasma correlate with axonal damage and cognitive decline, providing a quantifiable measure of neurodegeneration." (PMID 41480492, 2025). "A linear mixed model demonstrated that plasma tau phosphorylated at threonine 181 (pTau181) and neurofilament light chain (NFL) exhibit the prognostic value in predicting cognitive decline longitudinally." (PMID 39594668, 2024). "In this group of PD patients with cognitive decline, higher levels of serum neurofilament light chain (NfL) were detected, indicative for increased neuronal damage." (PMID 37803149, 2024). "Neurofilament light chain (NfL) is emerging as a clinically useful plasma biomarker for damage occurring in the brain, including in AD where it tracks with cortical thinning and cognitive decline, while in mouse models of AD it correlates with plaque load." (PMID 36803190, 2023). "Among these biomarkers, blood neurofilament light chain (NfL) has the potential to predict disease severity and duration as well as motor and cognitive decline." (PMID 35072765, 2022). "Plasma neurofilament light chain (NF-L) levels were assessed as a diagnostic biomarker for traumatic brain injury (TBI) and as a prognostic biomarker for somatomotor recovery, cognitive decline, and epileptogenesis." (PMID 36499527, 2022). "Several proteins that were already known to be involved in PD have been investigated in CSF as potential biomarkers for diagnosis, disease progression, or cognitive decline, such as α-syn, neurofilament light chain (NFL), DJ-1, tau, and amyloid β42." (PMID 30465235, 2019). "Among the more recently studied biomarkers, e.g., neurofilament light chain (NfL, a marker of axonal damage) there are studies suggesting that exercise slows cognitive decline among older adults with increased NfL together with higher total tau concentrations in the blood." (PMID 40551205, 2025). "As the neurofilament light chain is increasingly recognized as a predictor for cognitive decline, elucidating the extent of axonal damage where these lesions occur is critical to completely understand the significance of neurofilaments as biomarkers in the context of SVD." (PMID 39175459, 2025).
cognitive decline (continued). "Additionally, elevated neurofilament light chain (NfL) levels in CSF have been shown to predict cognitive decline, further underscoring the importance of these biomarkers in understanding and managing the disease." (PMID 39767666, 2024). "In addition, we included neurofilament light chain because this protein is becoming increasingly valuable as a peripheral biomarker of neuronal damage and subjective cognitive decline." (PMID 36253765, 2022). "Neurofilament light chain (NfL) is released by injury to subcortical large-fiber axons, and has also emerged as a non-specific biomarker of neurodegeneration, white matter integrity and cognitive decline." (PMID 35898322, 2022). "For example, the downregulation of NEFL, MAP1B, and GAP43—genes essential for axonal stability, cytoskeletal organization, and synaptic plasticity—may underlie the progressive cognitive decline and neurodevelopmental delay frequently reported in POLG‐related encephalopathies." (PMID 41355579, 2026). "Finally, neuronal markers such as circulating Neurofilament Light chain (NfL) increase with age and show modest but consistent sex differences, with higher concentrations in men, underscoring the need for sex-specific reference ranges when assessing neurodegeneration and cognitive decline." (PMID 41470779, 2025). "This study aimed to investigate whether plasma neurofilament light chain (NfL) mediates the relationship between SSD and cognitive decline." (PMID 40438503, 2025). "Notably, NEFL was the only protein altered in both late and intermediate stages (MoCA score 16–25) but not in the mild stage of cognitive decline (MoCA score > 25)." (PMID 37175824, 2023).
amyotrophic lateral sclerosis (205 papers, 2005 to 2026). Amyotrophic lateral sclerosis (ALS) is a neurodegenerative disease characterized by progressive muscular paralysis reflecting degeneration of motor neurons in the primary motor cortex, corticospinal tracts, brainstem and spinal cord. "Elevated levels of neurofilament light chain (NF-L) in CSF and blood are linked to the presymptomatic and symptomatic phase of patients suffering from amyotrophic lateral sclerosis (ALS)." (PMID 35585288, 2022). "Furthermore, connections with FUS, TARDBP, and NEFL, all linked to amyotrophic lateral sclerosis (ALS), highlight SOD1’s involvement in neurodegenerative disease pathways." (PMID 40710578, 2025). "Mutations in the neurofilament light chain gene itself result in axonal forms of hereditary motor sensory polyneuropathy and variants of the heavy neurofilament subunit are associated with the development of amyotrophic lateral sclerosis." (PMID 33233404, 2020). "Neurofilament light chain (NfL) has emerged as a promising diagnostic and prognostic biomarker for amyotrophic lateral sclerosis (ALS)." (PMID 39865616, 2025). "This study evaluates the diagnostic and prognostic value of serum (sNfL) and cerebrospinal fluid neurofilament light chain (cNfL) levels in amyotrophic lateral sclerosis (ALS) patients." (PMID 39865616, 2025). "Neurofilament light chain (NFL) has been shown to be increased in amyotrophic lateral sclerosis (ALS) and, to a lesser extent, in frontotemporal dementia (FTD)." (PMID 38937912, 2024). "In a specialized clinic, neurofilament light chain is largely confirmatory to clinical judgement in diagnosing amyotrophic lateral sclerosis and has limited ability to exclude alternative diagnoses." (PMID 37292457, 2023). "The current, important, value of neurofilament light chain is its potential to stratify patients with amyotrophic lateral sclerosis by disease activity and as a biomarker in therapeutic trials." (PMID 37292457, 2023). "Blood neurofilament light chain, creatine kinase, serum ferritin, C3 and cerebrospinal fluid neurofilament light chain and chitotriosidase 1 were all significantly elevated in amyotrophic lateral sclerosis patients." (PMID 35224491, 2022). "The most promising biomarker for amyotrophic lateral sclerosis (ALS) is neurofilament light chain (NfL) at present." (PMID 31742901, 2019). "The diagnostic and prognostic values of serum neurofilament light chain (sNfL), in comparison to cerebrospinal fluid (CSF) neurofilament light chain (cNfL), and other clinical parameters in amyotrophic lateral sclerosis (ALS) at the time of diagnosis remain elusive." (PMID 39865616, 2025). "At the proteomics level, autophagy has been reported as a degradative pathway for neurofilament subunit proteins, with accumulations of NEFL subunit being pathological hallmarks of amyotrophic lateral sclerosis and contributing to neurofibrillary lesions in AD." (PMID 39358810, 2024). "In contrast, CSF neurofilament light chain levels in amyotrophic lateral sclerosis overlapped with those in myelopathies (2900.11 ± 872.20 pg/mL; P = 0.821) and other mimic diseases (3169.75 ± 1096.65 pg/mL; P = 0.63), but not with inflammatory polyneuropathies (1156.4 ± 356.6 pg/mL; P = 0.000)." (PMID 39188590, 2024). "In plasma, single molecule array (SIMOA) neurofilament light chain determination [amyotrophic lateral sclerosis (86.00 ± 12.23 pg/mL) versus healthy control (12.69 ± 1.15 pg/mL); P = 0.000] was more accurate than plasma C-X-C motif chemokine ligand 12 (area under the curve 0.98 ± 0.01405)." (PMID 39188590, 2024). "Of 133 referrals, 93 patients were diagnosed with amyotrophic lateral sclerosis (median neurofilament light chain 218.1 pg/ml, interquartile range 130.7–311.9), three primary lateral sclerosis (65.6, 51.5–106.9) and 19 alternative diagnoses (45.2, 13.5–71.9) at first visit." (PMID 37292457, 2023).